KRAS (KRas proto-oncogene, GTPase)
Diseases named in the same sentence as KRAS in open-access papers (continued):
Sharing a sentence is not in itself a finding about the gene and the disease.
tumor (continued). "The model also failed to incorporate other clinical and pathological prognostic factors (e.g., tumor markers, PET–CT value, and central or peripheral tumor) and some important recognized prognostic molecular factors (e.g., KRAS mutations, EGFR mutations, and ALK rearrangements)." (PMID 31884561, 2020). "As a result, all patients entering the PROSPECT-R trial had a cataloged KRAS/NRAS variant that could be used to investigate the tumor content of the respective biopsy samples." (PMID 33014822, 2020). "Until now it is still unclear whether the KRAS mutation status should be determined by analyzing the primary tumor or metastatic tissue." (PMID 33002027, 2020). "We conclude that inhibiting endogenous TRAIL in KRAS-mutated cancers may not only inhibit tumor growth, invasion, and metastasis, but also enhance adaptive immunity against these cancers." (PMID 32194994, 2020). "For the entire group of 50 patients, plasma HMGB1 showed a modest variation over the neoadjuvant treatment course, which first led us to investigate whether tumor mutational KRAS status might identify cases with ICD response." (PMID 31893287, 2020). "The prognostic value of KRAS mutations may be influenced by many factors, including primary tumor site, tumor stage, and adjuvant treatment received." (PMID 32859214, 2020). "This editing of oncogenic mutations could be combined with inhibitors of KRAS or other oncogenic mutations, or immunotherapy, to further improve the anti-tumor efficacy." (PMID 32308773, 2020). "Alternatively, EGFR and KRAS mutations could also exist in different subclonal mCRC populations in the same tumor, as a result of tumor heterogeneity, driving the activation of the same pathway." (PMID 32457828, 2020). "KRAS mutation is associated with morphologic tumor growth patterns." (PMID 32858990, 2020). "One tumor was identified as a KRAS (G12R) co-mutation with BRAF (L567V)." (PMID 32083130, 2020). "By increasing the mutation burden of tumor cells, oncogenic KRAS also induces the production of a large number of neoantigens that may be recognized by CD8+ and CD4+ T cells." (PMID 33194642, 2020). "In a prospective-multicenter study, Thierry and colleagues show that cfDNA analysis could advantageously replace tumor-section analysis for KRAS and BRAF mutations." (PMID 32231042, 2020). "Furthermore, NEAT1 long form—and, thus, the paraspeckles—promote skin tumorigenesis by increasing survival of tumor cells expressing mutated KRAS in genetically engineered mouse models." (PMID 33142861, 2020). "Ampullary tumours too harbour high frequency of KRAS mutations (40–50%)." (PMID 32552660, 2020). "Two patients showed intertumoral heterogeneity, which harbored in one patient a KRAS G12C mutation status in the primary tumor, but a G12V KRAS mutation status in the corresponding lung lesion, and in the other patient a G12A mutation in the primary lesion and a WT in the lung metastasis." (PMID 33002027, 2020). "On the basis of the effects of EMab-17 against OSCC cell lines, we explored whether EMab-17 shows similar anti-tumor activity in CRC cell lines with KRAS p.G13D mutations, as there are few effective treatments for patients with mCRC with KRAS mutated tumors." (PMID 32839411, 2020). "By transducing HCT116 cells of wild-type or activated (G13D) KRAS with a sgRNA library targeting protein-coding genes and injecting them into mice, tumor xenografts were obtained and used to determine KRAS-lethal and enhancing mutations as well as for pathway analysis." (PMID 32765953, 2020). "Furthermore, we compared the tumor purity, immune score, and stromal score between the KRAS-mutated and wild-type groups." (PMID 33254149, 2020). "Only two patients showed intertumoral heterogeneity, which harbored in one patient a KRAS G12C mutation status in the primary tumor, but a G12V KRAS mutation status in the corresponding lung lesion, and in the other patient a G12A mutation in the primary lesion and a WT in the lung metastasis." (PMID 33002027, 2020).
tumor (continued). "Especially, KRAS mutations occur in more than 90% of all tumour samples." (PMID 32727085, 2020). "Among 13 patients who developed HPD after treatment, three showed FBXW7 mutation, a tumor suppressor gene encoding a protein belonging to the proteasome systems, and three others showed amplification in the KRAS gene, a GTPase that regulates several cellular signaling pathways." (PMID 33168050, 2020). "CtDNA samples derived from fourteen tumor patients were tested with the newly developed KRAS hotspot mutation assay, two samples were detected carrying at least one type mutations of codon 12 and one sample was detected carrying codon 13 mutation according to the amplification curve and melt curve." (PMID 32207862, 2020). "In vitro studies employing three-dimensional (3D) cancer organoid models derived from recto-sigmoid cancers and non recto-sigmoid cancers are warranted to understand the role of lipids in KRAS mutated signaling pathways and cancer metabolism within the 2 different tumour locations." (PMID 32594310, 2020). "One potential mechanism by which oncogenic KRAS could regulate tumor mutation burden is via promoting fatty acid accumulation in tumor cells." (PMID 33194642, 2020). "The EGFR and Mutation venation includes NSCLC, KRAS, Tumor, Target Therapy, NGS, DNA, and MicroRNA." (PMID 32014844, 2020). "Moreover, NSCLC harboring KRAS mutation present a higher tumor mutation burden, leading to tumor immunogenicity." (PMID 33194642, 2020). "Here they could demonstrate a concordance rate of 93% for the KRAS mutation status between the primary tumor and metastasis." (PMID 33002027, 2020). "Mutations in certain genes may alter tumor biology to more aggressive phenotypes, such as KRAS or BRAF mutation in colorectal cancer." (PMID 32024876, 2020). "In this model, activation of cancer cells carrying the mutated KRAS by IL-4 and IL-13, which were secreted by the Th2 cells present in the tumor microenvironment, triggered the JAK1-STAT6-MYC pathway that in turn activated glycolysis crucial for tumor progression." (PMID 33042121, 2020). "However, the tumor response rates achieved so far only range from 10 to 20%, and the response durations are usually short, even for tumors with KRAS mutations." (PMID 33244099, 2020). "While sustained proliferation caused by oncogenic KRAS-downstream signalling is a main driver of carcinogenesis, there is increasing evidence that it also mediates autocrine effects and crosstalk with the tumour microenvironment (TME)." (PMID 33116132, 2020). "Using this approach, we examined whether T cells induced by vaccination could respond to the KRAS mutations and ultimately inhibit tumor growth." (PMID 33298945, 2020). "Because IKKβ promotes TIC function and because it activates the NF-κB pathway, which has also been implicated in promoting metastasis in different tumour models, we hypothesized that it would also promote KRAS-induced migration and invasion." (PMID 32823550, 2020). "Yet, our preliminary analysis of the impact of KRAS mutation status revealed that certain lincRNA expression patterns might be caused by individual tumour-associated mutations." (PMID 32727085, 2020). "On one side, this may imply that coexisting EGFR and KRAS activating mutation might provide additional advantages to tumor progression in mCRC." (PMID 32457828, 2020). "The importance of the liquid biopsy may provide critical clinical insight into molecular subtypes of the tumor, especially when the discordance in KRAS mutations between primary and recurrent tumors after resection can be as high as 20%." (PMID 32471160, 2020). "In PDAC associated with the KRAS mutation, decitabine therapy inhibits tumor growth." (PMID 33302876, 2020).
tumor (continued). "Thus, our observations suggest that CXCR7 overexpression is one of the survival mechanisms in KRAS-dependent tumor cells with EGFR loss or cells treated with EGFR-TKIs." (PMID 30935067, 2019). "Additionally, tumor tissue of patient 4, harboring a G13D KRAS mutation, showed a response after cultivation with Cetuximab." (PMID 31675944, 2019). "KRAS mutations were present in 65.2% of H-PB versus 36.4% of H-INT tumours (p < 0.04)." (PMID 30837681, 2019). "Moreover, NSCLC overexpressing wild- type EGFR are often primary resistant, especially in tumor with concurrent KRAS mutation." (PMID 31196210, 2019). "At baseline, blood samples from 125 patients were available for KRAS exon 2 status assessment on plasma as part of our study; 46 of these 125 patients had a KRAS exon 2 mutated tumor according to their medical files (i.e., determined by routine local assessment)." (PMID 31142037, 2019). "A sole malignancy consists of many sub-clone tumor cells, which may explain how two mutually exclusive BRAF and KRAS gene mutations can co-exist in a single tumor." (PMID 30658510, 2019). "In these unusual cases, it is unclear whether BRAF and KRAS mutations co-exist within the same tumor cells, implying tumor progression, versus a “collision” event, involving separate tumor populations arising from different cells of origin." (PMID 31839880, 2019). "Forty one patients with baseline LB sample presented archival tumor tissue mutated for KRAS, NRAS, or BRAF (68.3%), and 38/41 (92.6%) demonstrated concordant status for the expected patient specific mutations, as supported by more than one mutational event out of two replicates." (PMID 31355139, 2019). "We assessed KRAS mutation status in EBC against its presence in tumor tissue." (PMID 30368666, 2019). "Treatment of mice with KRA-533 resulted in accumulation of active KRAS in tumor tissues in association with increased apoptosis and autophagy, suggesting KRA-533-mediated tumor suppression may occur through induction of apoptosis and autophagic cell death." (PMID 30971271, 2019). "Because the EGFR inhibitor suppressed CD44v expression even in KRAS-mutated cancer cells, the EGFR inhibitors could also be applicable to the KRAS-mutated tumours to target the drug-tolerant CD44v-positive cancer cells." (PMID 31607750, 2019). "Consider, for instance, the question of whether a particular lung tumor is driven by KRAS mutations, a question which might be answered from some exome sequencing that was performed on a tumor biopsy." (PMID 31622330, 2019). "Although the detection rate of the KRAS mutation in ctDNA was relatively consistent with that in tumor tissue, whether the KRAS mutant allele fraction (MAF) differed was still not reported." (PMID 31850201, 2019). "RNA-seq confirmed selective amplification of the KRASG13D mutant allele and revealed a reduction in the wild-type KRAS allele; this may relate to a tumour-suppressor function for wild-type RAS36–39." (PMID 31048689, 2019). "Low expression levels of AREG and EREG associated with KRAS mutations might indicate a tumor that is less dependent on EGFR and is therefore particularly prone to developing resistance to anti-EGFR MoAbs." (PMID 31771279, 2019). "Second, stable disease could also be a result of tumor heterogeneity, whereby only a small fraction of tumor cells harbor KRAS mutations and the majority are RAS wild‐type." (PMID 31350822, 2019).
tumor (continued). "Moreover, we investigated the heterogeneity of KRAS mutations between tumor center and invasion front, as well as between primary tumor and metastasis, which revealed that discrepancies in KRAS status among individual patients were rarely observed." (PMID 31891652, 2019). "Importantly, as a potential personalized biomarker, KRAS mutations can be used to not only predict the primary tumor but monitor minimal residual tumor during therapy." (PMID 30976068, 2019). "Within our study cohort, KRAS or BRAF mutations were present in 35 of 65 (54%) tumor specimens." (PMID 31134762, 2019). "In addition, the morphological patterns in the primary and recurrence were the same in this case, and the same KRAS G12R mutation is shared by the primary tumor and two different recurrences." (PMID 30467323, 2019). "To confirm that our CTC cell line originated from the primary lesion, we previous studies have demonstrated that the sequencing of CTC-TJH-01 cells exhibits wild-type EGFR and a missense mutation at codon 12 in exon 2 of KRAS, which is consistent with the mutation status found in the primary tumor." (PMID 30718976, 2019). "Moreover, KRAS MAF in ctDNA was obviously associated with tumor staging and distant metastasis in PC patients." (PMID 31850201, 2019). "Mutations in codon 12 of KRAS were detected in 35 (85.4%) of 41 tumours harbouring KRAS mutations." (PMID 30837681, 2019). "Our observation of multiple KRAS mutations in most juice samples is consistent with an earlier report focusing on three hotspot KRAS mutations of codon 12 in matched pancreatic juice and tumor specimens." (PMID 30611220, 2019). "KRAS acts as a critical driving force in these cancers, as mutated forms of KRAS are constitutively activated, permitting significant downstream effects including increased cell proliferation, tumor progression, and higher rates of metastasis." (PMID 31247990, 2019). "In our study, KRAS exon 2 mutations were identified in 84 out of 129 tumor specimen (86.6%)." (PMID 30949599, 2019). "Thus, KRAS positive EBC changed probability of the presence of this mutation in tumor from 0.63 (95% CI 0.36–0.91) to 0.92 (95% CI 0.75–1.0, PPV), p = 0.04." (PMID 30368666, 2019). "Because the in vitro data showed that YB-1 was highly phosphorylated in the different CRC cell lines tested and that the phosphorylation was stimulated by point mutations in KRAS, we tested the phosphorylation status of YB-1 in tumor tissues from three CRC patients." (PMID 31010234, 2019). "Additionally, KRAS mutation analysis in ctDNA allows repeated analysis of tumor mutations to identify acquired resistance and emerging potential therapeutic targets." (PMID 32328554, 2019). "Importantly, our data identified a “gray zone” below 1% MAF where Idylla shows reduced KRAS mutation detection accuracy vs OncoBEAM and SOC FFPE tumor KRAS testing." (PMID 31222012, 2019). "Moreover, we found tumors with multiple mutations in the same gene including six tumors with two KRAS mutations, one tumor with three KRAS mutations, and one tumor with two BRAF mutations." (PMID 31036005, 2019). "Some of the more well described targets are SPRED1, p85β, and PI3KR2 governing vascular integrity, VEGF-A regulating AKT-pathway signaling, CXCR4 and IRS-1 involved in CRC cell proliferation and migration, and KRAS impacting on the viability of the mutated tumor cells." (PMID 35582589, 2019).
tumor (continued). "Factors found to be significantly associated with worse OS were age 15–39 years (p = 0.002), right-sided tumour (p < 0.001), poor differentiation (p < 0.001), signet ring cell feature (p < 0.001), KRAS mutation (p = 0.013), BRAF mutation (p < 0.001) and pMMR (p = 0.016)." (PMID 31406299, 2019). "KRAS is expressed as two splice variants, KRAS4a and KRAS4b, where variant 4b is more prevalent in normal cells compared to greater levels of variant 4a seen in tumor cells." (PMID 31009485, 2019). "Right-sided tumours have been associated with the presence of KRAS and BRAF mutations." (PMID 30843120, 2019). "It should be noted, though, that the presence of multiple KRAS mutations in a pancreatic juice sample also might reflect clonal heterogeneity of the primary tumor." (PMID 30611220, 2019). "However, we and other groups described that some RAS wt mCRC patients with clinical resistance to anti-EGFR agents had a liquid biopsy positive for KRAS mutations and carried the same variant at very low allelic frequency in the primary tumor." (PMID 31226844, 2019). "Interestingly, in tumor-derived intestinal organoid cultures, KRAS mutations were found in all CMS groups except for CMS3." (PMID 31614493, 2019). "KRAS mutation test was performed on paraffin-embedded tumor samples using PCR methods." (PMID 30917791, 2019). "On the other hand, the parallel analysis of five excision specimens of tumor with cancer cellularity > 90% per one NSCLC patient may contribute to high frequency of KRAS mutations observed in our study." (PMID 30368666, 2019). "Small interfering-RNAs (siRNAs) for specific KRAS point mutations have shown attractive anti-tumor activity in non-small cell lung cancer (NSCLC) and may be directly translated in CRC models." (PMID 31275854, 2019). "The KRAS mutation was confirmed by ddPCR analysis of tumor tissue." (PMID 31226844, 2019). "The percentage of KRAS-mutant clones within the tumor, and the type of variant of KRAS-mutant codon were proposed to be factors that impact heterogeneous outcome, but no clear association could be established." (PMID 31315599, 2019). "Indeed, an analysis of 27 PDAC tumour samples also suggested that those with a COSM521 mutation had worse survival than those with other KRAS mutations." (PMID 30774772, 2019). "However, most of these studies were rather heterogeneous in terms of histology, tumor stage, and methodologies of KRAS mutation detection." (PMID 31600989, 2019). "Whether direct inhibition of KRAS with these new compounds is sufficient remains a question, given the presence of KRAS independence in tumor cells harboring KRAS mutations." (PMID 31612108, 2019). "However, the KRAS mutation identified in the primary tumor corresponded to the predominating mutation in the juice to a much lesser degree (11 cases, 52%)." (PMID 30611220, 2019). "For instance, “KRAS proto-oncogene, GTPase” KRAS mutations can be detected in ctDNA even though the biopsy was KRAS wild type at diagnosis: these can lead to resistance to therapy and tumor relapse." (PMID 31795332, 2019).